NEFL (neurofilament light chain)
Diseases named in the same sentence as NEFL in open-access papers (continued):
Sharing a sentence is not in itself a finding about the gene and the disease.
amyotrophic lateral sclerosis (continued). "In amyotrophic lateral sclerosis (ALS), exosomal biomarkers, such as neurofilament light chain, have been identified in both cerebrospinal fluid and blood." (PMID 40182844, 2025). "In genetic amyotrophic lateral sclerosis (ALS), the clinical phenotypes, disease progression and neurofilament light chain (NfL) levels are incompletely characterized." (PMID 41388206, 2025). "In April 2023, the antisense oligonucleotide tofersen was approved by the U.S. Food and Drug Administration (FDA) for treatment of SOD1-amyotrophic lateral sclerosis (ALS), after a decrease of neurofilament light chain (NfL) levels had been demonstrated." (PMID 38384337, 2024). "Previous attempts to establish a diagnostic role for neurofilament light chain have been limited to comparison with healthy individuals or controls with alternative diagnoses unlikely to be confused with amyotrophic lateral sclerosis in real-world clinical practice." (PMID 37292457, 2023). "Little is known about the influence of Riluzole on serum neurofilament light chain (sNfL) levels, a biomarker of prognosis in amyotrophic lateral sclerosis (ALS), and variations with time of sNfL concentrations are controversial." (PMID 35751632, 2022). "Modelling the inclusion of plasma neurofilament light chain as a therapeutic trial outcome measure demonstrated that a significant reduction in sample size and earlier detection of disease-slowing is possible, compared with using the revised Amyotrophic Lateral Sclerosis Functional Rating Scale." (PMID 35224491, 2022). "We previously reported the diagnostic and prognostic performance of neurofilament light chain (NfL), TAR DNA-binding protein 43 (TDP-43), and total tau (t-tau) in cerebrospinal fluid (CSF) and plasma as amyotrophic lateral sclerosis (ALS) biomarkers." (PMID 34843548, 2021). "The de novo assembly of these neuronal intermediate filaments requires the presence of the neurofilament light subunit (NEFL), whose expression is reduced in motor neurons in amyotrophic lateral sclerosis (ALS)." (PMID 32429483, 2020). "The quantitative monitoring of neurofilament light chain (Nf-L) is critical for the early diagnosis and prognosis of neurodegenerative disorders, such as amyotrophic lateral sclerosis (ALS), yet achieving femtomolar sensitivity in a portable, label-free format remains a formidable challenge." (PMID 41572578, 2026). "In amyotrophic lateral sclerosis (ALS), neurofilament light chain (NfL) was introduced as a prognostic biomarker." (PMID 39910638, 2025). "For example, the FDA recently granted accelerated approval to the amyotrophic lateral sclerosis therapeutic tofersen (QALSODY), based on its ability to reduce neurofilament light chain (NfL) protein levels in the blood." (PMID 38973610, 2024). "These include genes in the pathways for amyotrophic lateral sclerosis (NEF3, NEFL, NEFH), Huntington's disease (CALM3, CLTC, CLTB), neurodegenerative disorders (APLP1, NEFH, FBXW7), Parkinson's disease (GPR37) and prion disease (APLP1, NFE2L2)." (PMID 19948073, 2009). "Tofersen is a gene-targeted therapy for superoxide dismutase 1 (SOD1)-associated amyotrophic lateral sclerosis (ALS), but neurofilament light chain (NfL) may not fully capture the biological response to treatment." (PMID 42196191, 2026). "Similar to total tau (t-tau), increased concentrations of neurofilament light chain (NfL) are not specific to AD and can also be elevated in other neurodegenerative disorders, such as amyotrophic lateral sclerosis (ALS) and frontotemporal dementia (FTD)." (PMID 40943171, 2025). "Neurofilament light chain ≥110.9 pg/ml had a positive predictive value of 0.92 for amyotrophic lateral sclerosis; <110.9 pg/ml had a negative predictive value of 0.48." (PMID 37292457, 2023).
Brain atrophy (159 papers, 2013 to 2026). Partial or complete wasting (loss) of brain tissue that was once present. "In SPMS and PPMS, arachidonic acid-derived species (5-, 8-, and 15-HETE) were elevated and associated with EDSS, neurofilament light chain, and brain atrophy, while protective HODE and docosapentaenoic acid derivatives declined." (PMID 41009767, 2025). "Neurofilament light chain (NfL) is a novel biomarker reflecting neuroaxonal damage and associates with brain atrophy, and glial fibrillary acidic protein (GFAP) is a marker of astrocytic activation, associated with several neurodegenerative diseases." (PMID 35551210, 2022). "Furthermore, levels of CSF or plasma neurofilament light chain (NfL) are strongly associated with the progression of AD, and NfL concentration in CSF can reliably predict brain atrophy and cognition in AD." (PMID 38281031, 2024). "Among these, neurofilament light chain (NfL), ubiquitin C-terminal hydrolase L1, total tau, and glial fibrillary acidic protein (GFAP) were consistently associated with CI and brain atrophy across various TBI severities and stages." (PMID 42196255, 2026). "Neurofilament light chain (NfL) is a marker of axonal injury and a biomarker for disease activity and progression, with both CSF and serum levels correlating with relapse rates, brain atrophy, and long-term disability outcomes." (PMID 40440559, 2025). "Baseline levels of neurofilament light chain in CSF and plasma have been shown to be effective in predicting clinical disease status, subsequent clinical progression and brain atrophy." (PMID 38370446, 2024). "We show that in multiple system atrophy, baseline plasma neurofilament light chain levels were better predictors of clinical progression, survival and degree of brain atrophy than the neurofilament light chain rate of change." (PMID 35903017, 2022). "Consequently, inflammatory activity is suppressed, biomarkers (such as neurofilament light chain, NfL) normalize, and brain atrophy slows." (PMID 41596238, 2026). "Core biomarkers of AD have been studied in adults with DS, namely cerebrospinal fluid (CSF) Aβ1–42 and amyloid PET, CSF phosphorylated tau and tau PET, neuronal injury biomarkers such as CSF total tau and neurofilament light chain (NfL), or regional brain atrophy on MRI." (PMID 35740400, 2022). "Moreover, BAG was not correlated with neurofilament light chain, indicating that brain atrophy patterns leading to increased BAG are not primarily caused by an overall faster neurodegeneration." (PMID 41361244, 2025). "Expanded definitions of NEDA incorporate brain atrophy (NEDA-4) and/or other components, such as fluid biomarkers (e.g., neurofilament light chain levels), cognitive function, and psychological or quality-of-life measures." (PMID 39512280, 2024). "Plasma Neurofilament Light Chain (NfL), in contrast, has a distinct profile, providing information about the rate of brain atrophy rather than the core pathological processes in AD." (PMID 39701863, 2025).
Stroke (148 papers, 2008 to 2026). Sudden impairment of blood flow to a part of the brain due to occlusion or rupture of an artery to the brain. "Biomarkers such as neurofilament light chain (Nf-L), tau protein, and S100b reflect the extent of brain injury and are associated with secondary neurodegeneration and correlate with worse functional outcomes post stroke." (PMID 40356948, 2025). "Besides, cerebral small vessel disease (CSVD) is one of the main causes of stroke, and neurofilament light chain protein (NFL) is the main component of neurofilament core, which is related to the occurrence of subcortical small infarcts and new CSVD." (PMID 36753509, 2023). "Further, future studies may also include novel biomarkers as for instance neurofilament light chain, which has shown an association with the long-term outcome after stroke, while its relevance in the acute and short-term course is still pending." (PMID 34899557, 2021). "A 7-year prospective study suggested that the neurofilament light chain (NfL) level may indicate brain injury and risk of stroke." (PMID 34640636, 2021). "We demonstrated that serum neurofilament light chain (NfL) -a biomarker widely used in clinical stroke studies- strongly correlated with functional outcomes, establishing a translational link that has not been previously reported in rats." (PMID 42101718, 2026). "Based on genomics research, NfL, encoded by the NEFL gene, has emerged as a blood-based biomarker of neuronal and axonal damage following stroke." (PMID 40949500, 2025). "Serum neurofilament light chain (sNfL) has recently been suggested as a marker of neuroaxonal injury after stroke with potential applications both for patient monitoring and for observational and interventional studies." (PMID 40304765, 2025). "Actually, brain-derived markers, particularly neurofilament light chain, tau protein, S100b, in post-stroke patients have yielded promising results." (PMID 37719764, 2023). "Neurofilament light chain (NfL) has been identified as a blood-based biomarker that reflects neuroaxonal damage resulting from stroke." (PMID 35651349, 2022). "Therefore, the aim of the present review was to give an overview of the current understanding and knowledge of neurofilament light chain as a potential biomarker of perioperative stroke." (PMID 35875791, 2022). "Furthermore, Peng and colleagues evaluated the predictive value of the combination of a serum biomarker for axonal damage (i.e., neurofilament light chain (NfL)) and neuroimaging markers (volume of infarction and WMHs) for neuronal abnormalities in post-stroke cognitive outcomes." (PMID 36810471, 2023). "Increased sensitivity of methods assessing the levels of neurofilament light chain (NfL), a neuron-specific intermediate filament protein, in human plasma or serum, has in recent years led to a number of studies addressing the utility of monitoring NfL in the blood of stroke patients." (PMID 34207058, 2021). "Other brain-specific biomarkers used following stroke include neuron-specific enolase (NSE), tau, neurofilament light chain (NfL), glial fibrillary acidic protein (GFAP), and ubiquitin C-terminal hydrolase L1 (UCH-L1)." (PMID 39968454, 2025). "We and others previously showed that brain-derived neuronal and glial markers, such as neurofilament light-chain (NF-L) and glial fibrillary acidic protein (GFAP), can be predictive biomarkers for stroke severity on admission and functional outcome." (PMID 33918875, 2021). "The role of neurofilament light chain (NfL) and glial fibrillary acidic (GFAP) as potential biomarkers especially in severe stroke patients is unknown." (PMID 38400734, 2024). "Thus, we identified neurofilament light chain (NfL), as a biomarker that could complement EEG in the longitudinal assessment of stroke recovery." (PMID 38562428, 2024).
frontotemporal dementia (146 papers, 2013 to 2026). Frontotemporal dementia (FTD) comprises a group of neurodegenerative disorders, characterized by progressive changes in behavior, executive dysfunction and language impairment, as a result of degeneration of the medial prefrontal and frontoinsular cortices. "We tested the hypothesis that plasma neurofilament light chain (NfL) identifies asymptomatic carriers of familial frontotemporal lobar degeneration (FTLD)–causing mutations at risk of disease progression." (PMID 33827960, 2021). "In genetic frontotemporal dementia, higher baseline cerebrospinal fluid rejuvenation proteins predicted slower decline across cognitive, functional, and neurofilament light chain trajectories; estimates were similar across genotypes." (PMID 39816189, 2025). "Similarly, neurofilament light chain (NfL), an unspecific marker of axonal injury, showed higher values in frontotemporal dementia (FTD) than in AD and DLB and a strong association between the values in the CSF and blood." (PMID 36221099, 2022). "A combination of using plasma tau phosphorylated at threonine 181 (p-tau-181), neurofilament light chain (Nfl), and glial fibrillary acidic protein (GFAP) for the discrimination of AD, frontotemporal dementia, and dementia with Lewy bodies, has been recommended." (PMID 36982820, 2023).
Parkinson disease (146 papers, 2004 to 2026). A progressive degenerative disorder of the central nervous system characterized by loss of dopamine producing neurons in the substantia nigra and the presence of Lewy bodies in the substantia nigra and locus coeruleus. "Here we examine Neurofilament-Light chain(NF-L), which has been implicated as a biomarker in the progression of Parkinson’s disease and other neurodegenerative diseases." (PMID 39736999, 2023). "CSF levels of parkinsonism-associated deglycase, tau, myelin basic protein (MBP), and neurofilament light chain (NfL), which reflect neurodegeneration in the brain, were significantly higher in patients with MSA than in those with Parkinson’s disease." (PMID 41439986, 2025). "It has recently been demonstrated that cerebrospinal fluid (CSF) and plasma neurofilament light chain (NfL) represent the most effective blood marker for predicting disease progression in several neurodegenerative disorders, including Parkinson’s disease (PD)." (PMID 39249107, 2024). "Neurofilament light chain (NFL) is elevated in neurodegenerative diseases, including Parkinson’s disease (PD)." (PMID 39164268, 2024). "For example, neurofilament light chain can help distinguish the atypical parkinsonisms such as multiple system atrophy and progressive supranuclear palsy from PD whereas DAT SPECT cannot." (PMID 36203214, 2022). "Cerebrospinal fluid neurofilament light chain and tau protein were found as mortality biomarkers in parkinsonism, including PSP, but it was unable to tell the difference among each specific parkinsonian type." (PMID 34650511, 2021). "Neurofilament light chain (NfL) and α-synuclein oligomeric seeds (α-syn-s) are promising biomarkers for patients with parkinsonism." (PMID 34635674, 2021). "The potential biomarkers of Parkinson’s disease are α-synuclein and neurofilament light chain (NFL)." (PMID 34858161, 2021). "In the Parkinson’s Progression Marker Initiative cohort, mean baseline serum neurofilament light chain was higher in Parkinson’s disease patients (13 ± 7.2 pg/mL) than in controls (12 ± 6.7 pg/mL), P = 0.0336." (PMID 32798333, 2020). "The objective of this study was to assess neurofilament light chain as a Parkinson’s disease biomarker." (PMID 32798333, 2020). "Serum neurofilament light chain increased longitudinally in Parkinson’s disease patients versus controls (P < 0.01)." (PMID 32798333, 2020). "Neurofilament light chain (NFL) as a biomarker of axonal degeneration was increased in atypical parkinsonian syndromes and differentiated from Parkinson's disease (AUC of 0.93), which has been confirmed in another study." (PMID 23812308, 2013). "Alterations in the levels of certain proteins in CSF, such as a-synuclein, tau protein, and neurofilament light chain (NF-L), may act as biomarkers for Parkinson’s disease." (PMID 40469842, 2025). "In blood, neurofilament light chain (NfL) shows limited disease specificity, with some isolated instances, for example, atypical parkinsonian disorders compared to Parkinson's disease, but remains a useful biomarker for general neurodegeneration and acute neurological injury." (PMID 40401628, 2025). "Neurofilament light chain, but not phosphorylated tau 181 levels were increased in people with Parkinson’s disease with poor outcomes, and correlated with white matter loss." (PMID 38715714, 2024). "Some studies demonstrated that the neurofilament light chain protein (NfL) is increased in patients with atypical parkinsonian syndromes and may help differentiate them from Parkinson’s disease." (PMID 35976324, 2022). "The prognostic role of plasma neurofilament light chain (NfL), phospho-tau, beta-amyloid, and GFAP is still debated in Parkinson’s disease (PD)." (PMID 39249107, 2024).
Parkinson disease (continued). "The main purpose of this systematic review and meta-analysis was to assess neurofilament light chain (NfL) differences in the CSF and blood of patients with MSA versus the healthy control group (HC), patients with Parkinson’s disease (PD) and patients with Lewy body dementia (LBD)." (PMID 40149766, 2025).